XRCC2 (X-ray repair cross complementing 2)
Description:
Involved in the homologous recombination repair (HRR) pathway of double-stranded DNA, thought to repair chromosomal fragmentation, translocations and deletions. Part of the RAD51 paralog protein complex BCDX2 which acts in the BRCA1-BRCA2-dependent HR pathway. Upon DNA damage, BCDX2 acts downstream of BRCA2 recruitment and upstream of RAD51 recruitment. BCDX2 binds predominantly to the intersection of the four duplex arms of the Holliday junction and to junction of replication forks. The BCDX2 complex was originally reported to bind single-stranded DNA, single-stranded gaps in duplex DNA and specifically to nicks in duplex DNA.
Synonyms: FANCU; POF17; SPGF50
Tractability: Small molecule: a structure with a bound ligand is known. PROTAC: ubiquitination databases record sites on it.
Gene: Protein-coding gene on chromosome 7 (152,644,776 to 152,676,193, reverse strand). Ensembl gene ENSG00000196584.
Subcellular location: Nucleus; Cytoplasm, cytoskeleton, microtubule organizing center, centrosome
Subcellular location (Human Protein Atlas): Nucleoplasm; Vesicles
Pathways (Reactome):
DNA Repair: HDR through Homologous Recombination (HRR); Homologous DNA Pairing and Strand Exchange; Presynaptic phase of homologous DNA pairing and strand exchange; Resolution of D-loop Structures through Holliday Junction Intermediates; Resolution of D-loop Structures through Synthesis-Dependent Strand Annealing (SDSA)
Disease: Defective HDR through Homologous Recombination Repair (HRR) due to PALB2 loss of BRCA1 binding function; Defective HDR through Homologous Recombination Repair (HRR) due to PALB2 loss of BRCA2/RAD51/RAD51C binding function; Defective homologous recombination repair (HRR) due to BRCA1 loss of function; Impaired BRCA2 binding to PALB2
Gene Ontology:
Molecular function: four-way junction DNA binding; protein binding; ATP binding; ATP-dependent DNA damage sensor activity; DNA binding
Biological process: centrosome cycle; DNA repair; DNA strand invasion; double-strand break repair via homologous recombination; mitotic cell cycle; supramolecular fiber organization; meiotic cell cycle
Cellular component: centrosome; Rad51B-Rad51C-Rad51D-XRCC2 complex; replication fork; nucleoplasm; nucleus
Genetic constraint (gnomAD): Loss-of-function variants: 23 observed, 26.95 expected, observed/expected ratio (o/e) 0.85, 90% interval 0.61 to 1.21. The upper end of that interval is the gene's LOEUF score, 1.21, which puts it in group 5 of 6, group 1 being the genes least tolerant of losing a copy. Missense variants: 313 observed, 336.55 expected, observed/expected ratio (o/e) 0.93, 90% interval 0.85 to 1.02. Synonymous variants: 104 observed, 121.21 expected, observed/expected ratio (o/e) 0.86, 90% interval 0.73 to 1.01.
Gene-disease validity (ClinGen):
ClinGen rates the evidence that XRCC2 causes each of these diseases.
Fanconi anemia complementation group U (autosomal recessive): Limited. Any Fanconi anemia in which the cause of the disease is a mutation in the XRCC2 gene.
hereditary breast carcinoma (autosomal dominant): Refuted. Breast carcinoma that has developed in relatives of patients with history of breast carcinoma.
familial ovarian cancer (autosomal dominant): No Known Disease Relationship. An instance of ovarian cancer that is caused by an inherited modification of the individual's genome.
Homologues: Orthologues: chimpanzee XRCC2 (99% identical), macaque XRCC2 (97% identical), pig XRCC2 (85% identical), dog XRCC2 (83% identical), rat Xrcc2 (79% identical), guinea pig XRCC2 (78% identical), mouse Xrcc2 (78% identical), tropical clawed frog xrcc2 (63% identical), zebrafish XRCC2 (50% identical). Paralogues in human: RAD51B (21% identical), RAD51C (21% identical), RAD51 (19% identical), DMC1 (18% identical), XRCC3 (16% identical), RAD51D (15% identical).
Diseases named in the same sentence as XRCC2 in open-access papers:
XRCC2 is named in the same sentence as 93 diseases in open-access papers, as found by Europe PMC text mining. Sharing a sentence is not in itself a finding about the gene and the disease. The quoted sentences say what the papers report.
breast carcinoma (54 papers, 2010 to 2025). "Another paralog of RAD51 is XRCC2, encoded by the XRCC2 gene, which has a disputable relationship to breast cancer risk." (PMID 39684352, 2024). "Studies on genetic variations in XRCC2 (rs3218536, Arg188His) have revealed some evidence of association with breast cancer risk and poor survival." (PMID 36281462, 2022). "Most studies consider XRCC2 to be a breast cancer susceptibility gene and have demonstrated that it plays an important role in its pathophysiology." (PMID 34051735, 2021). "With the help of massively parallel sequencing studies, rare mutations in the XRCC2 gene have been linked to increased breast cancer susceptibility among patients." (PMID 34068918, 2021). "Loss of the wild-type XRCC2 allele was observed only in one of the eight breast cancers from the Polish women who carried the c.96delT deletion." (PMID 31463769, 2019). "The OR for breast cancer risk given the XRCC2 mutation was 1.01 for women diagnosed under 51 years of age, and was 0.92 for those diagnosed above age of 50." (PMID 31463769, 2019). "XRCC2 has been reported to be a breast cancer susceptibility gene and is now included in several breast cancer susceptibility gene panels." (PMID 31463769, 2019). "Loss of the wild-type XRCC2 allele was observed in one of the eight breast cancers from women who carried XRCC2 c.96delT truncating mutation." (PMID 31463769, 2019). "It is also important to establish if missense mutations of XRCC2 confer increased breast cancer risk." (PMID 31463769, 2019). "We identified a recurrent truncating mutation of XRCC2 (c.96delT, p.Phe32fs) in 3 of 617 patients with familial breast cancer who were sequenced." (PMID 31463769, 2019). "Loss of the wild-type XRCC2 allele was observed only in one of the eight breast cancers from patients who carried the XRCC2 mutation." (PMID 31463769, 2019). "The results showed that the T allele of rs3218550, located in the 3′untranslated region (3′UTR) of X-ray repair cross-complementing gene-2 (XRCC2), increased breast cancer risk by 1.5-fold." (PMID 31370865, 2019). "Genetic variations in single-nucleotide-polymorphisms XRCC1 and XRCC2 are reported to influence breast cancer susceptibility in Cypriot women aged 40–70 years." (PMID 30119676, 2018). "The frequency of the CTC haplotype defined by the SNPs rs3218552|rs3218550|rs3218536 on the XRCC2 gene had a significant association with increased risk of breast cancer." (PMID 29433565, 2018). "The association of RAD51, XRCC3, and XRCC2 haplotypes with breast cancer risk was studied among 1516 breast cancer cases (including 592 familial cases) and 1234 population controls." (PMID 25918678, 2015). "A tendency for a decreased risk of breast cancer was observed with the occurrence of 188His/His genotype and 188His allele of XRCC2 and 241Met/Met genotype and 241Met allele of XRCC3 polymorphism." (PMID 24728564, 2015). "A meta-analysis of data from available literature revealed no direct relationship between polymorphic variants rs3218536 of the XRCC2 gene and the risk of breast cancer." (PMID 26339569, 2015). "Taken together, it is unlikely that RAD51, XRCC3, and XRCC2 have a significant contribution to breast cancer susceptibility." (PMID 25918678, 2015). "The XRCC2 gene rs3218536 polymorphism has been found to possibly increase the risk of developing cervical cancer and breast cancer in women in Pakistan." (PMID 26339569, 2015). "Given the unclear role of XRCC2 in breast cancer susceptibility, we sequenced the gene in an extensive series of 342 patients with a strong family history breast cancer." (PMID 25918678, 2015). "XRCC2 gene has been recently linked to breast cancer since rare germline mutations in the gene were identified in breast cancer families." (PMID 25918678, 2015).
breast carcinoma (continued). "An initial exome-sequencing study identified two germline XRCC2 mutations, while a larger-scale genetic analysis revealed ten rare XRCC2 variants in breast cancer families, some of which were definitely pathogenic." (PMID 23586058, 2013). "Several investigations point to the role of XRCC2 mutations and polymorphisms in various cancers such as breast cancer, colorectal cancer, brain cancer, oral and Lynch syndrome and esophageal adenocarcinoma." (PMID 23826488, 2013). "The principles described herein were applied in our recent publication identifying XRCC2 as a new breast cancer risk gene and have been made publically available as a suite of software tools." (PMID 23441864, 2013). "This leaves the possibility that some very rare XRCC2 alleles are true breast cancer susceptibility alleles, but conferring only moderate risks, which would require huge association studies to demonstrate." (PMID 23383274, 2013). "These include Rad52, the human Rad51 paralogs Rad51B, Rad51C, Rad51D, Xrcc2, and Xrcc3, and breast cancer susceptibility gene Brca2." (PMID 21129202, 2010). "Mutation spectrum of ATM, CHEK2, PALB2, and XRCC2 genes in patients with breast cancer." (PMID 38784039, 2024). "The present study pioneered the acquisition of the mutational landscape of the breast cancer susceptibility genes (ATM, CHEK2, PALB2, and XRCC2) using next-generation whole-exome sequencing from paraffin-fixed FFPE tissue blocks obtained from the breast cancer patients of Pashtun ethnicity." (PMID 38784039, 2024). "However, current evidence shows that in most studies the XRCC2 R188H polymorphism is considered to have little relationship with the risk of breast cancer." (PMID 36761956, 2023). "In addition, Sirisena and Kluzniak reported that SNPs in XRCC2 are associated with the risk of breast cancer pathogenesis." (PMID 37679817, 2023). "Concerning the XRCC2 Arg188His variant and clinicopathological characteristics, we did not observe a significant association between various BC clinicopathological characteristics and Arg188His polymorphism in the breast cancer patients." (PMID 35061678, 2022). "Single nucleotide polymorphisms on XRCC2 influence breast cancer risk and survival." (PMID 34207556, 2021). "In addition, MAPK12 is associated with breast cancer, while XRCC2 is part of BCDX2 complex, which acts downstream of BRCA2 recruitment and upstream of RAD51 recruitment." (PMID 31870274, 2019). "Previous studies have reported that SNVs in the DNA repair pathway genes such as XRCC2 may exert an effect on breast cancer susceptibility by acting as low penetrant alleles." (PMID 31370865, 2019). "Based on the results of this study, it is proposed that the variant T allele of rs3218550 may affect DNA repair capacity by regulating XRCC2 gene expression and thus, influence an individual’s susceptibility to sporadic breast cancer." (PMID 31370865, 2019). "We sequenced XRCC2 in 617 Polish women with familial breast cancer and found a founder mutation." (PMID 31463769, 2019). "We then genotyped 12,617 women with breast cancer and 4599 controls for the XRCC2 founder mutation." (PMID 31463769, 2019). "It is premature to consider XRCC2 as a breast cancer-predisposing gene." (PMID 31463769, 2019). "In addition, we analyzed clinical characteristics of breast cancers in carriers of a XRCC2 mutation, and performed loss of heterozygosity (LOH) analysis at the XRCC2 locus in tumors from XRCC2 mutation-positive women." (PMID 31463769, 2019). "The OR for risk of breast cancer in women with this XRCC2 mutation was 0.96 (95% CI 0.48–1.93)." (PMID 31463769, 2019). "In contrast to our findings, the SNP rs3218536 (also known as Arg188His in exon 3 of the XRCC2 gene), acting individually was reported to be associated with a slightly protective effect for breast cancer in a study of 1100 Cypriot women [OR = 0.79; 95% CI = 0.62–1.00; P = 0.05]." (PMID 29433565, 2018).
breast carcinoma (continued). "The putative function of this XRCC2 variant in susceptibility to breast cancer is somewhat unclear." (PMID 29433565, 2018). "We hypothesized that the altered HRR capacity produced by the variant allele of rs3218550 in the 3’UTR of the XRCC2 gene may influence an individual’s susceptibility to sporadic breast cancer." (PMID 29433565, 2018). "We screened the RAD51, XRCC3, and XRCC2 genes for germline variation in familial BRCA1/2-negative breast or ovarian cancer patients in order to evaluate the role of these genes in breast cancer predisposition in Finland and to identify putative recurrent founder mutations." (PMID 25918678, 2015). "This detected a significant association between familial breast cancer and XRCC2." (PMID 23383274, 2013). "Another study suggested that some XRCC2 coding SNPs can influence breast cancer risk and survival." (PMID 23586058, 2013). "We applied FAVR principles, described herein, to identify that rare mutations in XRCC2 increase the risk of human breast cancer, which is to our knowledge the first published report of massively parallel sequencing (MPS) being successfully applied to identify a new complex human disease gene." (PMID 23441864, 2013). "Failure of these processes will lead to mutations, and as a result XRCC2 might be responsible for cancer predisposition and especially a breast cancer susceptibility gene." (PMID 23586058, 2013). "In recent studies, common variants of XRCC2, particularly the encoding SNP of exon 3 (Arg188His), have been identified as potential cancer susceptibility sites, although in this case, the association with breast cancer susceptibility remains unclear." (PMID 36761956, 2023). "To verify whether a XRCC2 mutation confers elevated breast cancer risk and should be included in breast cancer test panels, we studied a large series of approximately 13,000 women with breast cancer and 5000 controls from Poland." (PMID 31463769, 2019). "Even though the XRCC2 A variant allele of rs3218536 has been shown by cell complementation assays to somewhat augment sensitivity to damage, there are no published studies which suggest a relationship between patients with the variant allele of rs3218550 and breast cancer." (PMID 29433565, 2018). "It is known that polymorphisms in XRCC2 may modify individual susceptibility to breast cancers." (PMID 25743260, 2015). "The contribution of RAD51, XRCC3, and XRCC2 to breast cancer susceptibility remains unclear." (PMID 25918678, 2015). "Common variants within XRCC2, particularly a coding single nucleotide polymorphism (SNP) in exon 3 (Arg188His, R188H, rs3218536), have in recent studies been identified may be associated with a significantly increased risk of breast cancer." (PMID 25743260, 2015). "Previous studies have also shown that XRCC2 is abnormally expressed in a variety of tumors, including rectal and breast cancers, and that it participates in many cell signaling pathways." (PMID 34051735, 2021). "The breast cancer susceptibility proteins BRCA1 (also known as FANCS), BRCA2 (FANCD1), and RAD51 (FANCR) and its paralogs, including XRCC2 (FANCU) and XRCC3, all serve a function in homologous recombination repair (HRR)." (PMID 33625522, 2021). "In different ethnicities, RAD51 (rs1801320) and XRCC2 (rs3218536) gene polymorphisms are certified to be a threat aspect of colorectal cancer and RAD51 (rs1801320) gene polymorphism in breast cancer evolution in Bangladeshi population." (PMID 32458654, 2020).
breast carcinoma (continued). "Four SNPs [rs3218550 (XRCC2), rs6917 (PHB), rs1801516 (ATM), and rs13689 (CDH1)] were significantly associated with risk of breast cancer." (PMID 29433565, 2018). "In this study, the T allele in the SNP rs3218550 (XRCC2) and the A allele in SNP rs6917 (PHB) were susceptible alleles for sporadic breast cancer." (PMID 29433565, 2018). "Like most of the known breast cancer susceptibility genes, RAD51, XRCC3, and XRCC2 also have a role in DNA double-strand break repair by homologous recombination." (PMID 25918678, 2015). "In the reported study, the Arg188His polymorphism of XRCC2 gene and Thr241Met of XRCC3 were correlated with breast carcinoma progression." (PMID 24728564, 2015). "Unfortunately, it is difficult to find in the literature reports directly binding -41657C/T SNP in DNA repair gene XRCC2 with breast cancer occurrence." (PMID 25743260, 2015). "While germline mutations in RAD51C and RAD51D are associated with high ovarian cancer risk and RAD51B polymorphisms with breast cancer, the contribution of RAD51, XRCC3, and XRCC2 is more unclear." (PMID 25918678, 2015). "Lower levels of XRCC2 expression have been found in breast cancer tissues, while higher levels of XRCC2 expression have been detected in several other cancers." (PMID 26320178, 2015). "We extracted seven genes, XRCC3, XRCC2, RAD51C, RAD51L1, RAD51L3, FANCG, BRCA2, that formed a connected PPI network with eight interactions, and had been associated with breast cancer as well as other types." (PMID 24784581, 2014). "We therefore in this study aimed to assess the potential interactions of seven common polymorphisms from five DNA repair genes (XRCC1, XRCC2, XRCC3, XPA and APEX1) in association with breast cancer among Han Chinese women." (PMID 24642895, 2014). "Some SNPs also showed a significant effect on survival outcomes, such as RAD51-135 G>C in breast cancer, XRCC2 R188H in pancreatic cancer, and SNPs of RAD51-135 G>C and XRCC3 T241M in acute myeloid leukemia." (PMID 21647442, 2011). "We did not detect any missense variants of XRCC2 which are predicted to be pathogenic using in silico tools in 617 Polish families with hereditary breast cancer who were fully sequenced." (PMID 31463769, 2019). "Further, breast cancers in XRCC2-mutation carriers and non-carriers were similar with respect to age of onset, clinical characteristics, and survival." (PMID 31463769, 2019). "Breast cancers in XRCC2 mutation carriers and non-carriers were similar with respect to age of diagnosis and clinical characteristics." (PMID 31463769, 2019). "Two single nucleotide polymorphisms (SNPs) [rs3218550:NC_000007.14:g.152646870C>T, X-ray repair cross-complementing gene-2 (XRCC2)/7q36.1; and rs6917:NC_000017.11:g.49404181G>A, prohibitin-1 gene (PHB)/17q21.33] showed the strongest evidence for association with breast cancer risk." (PMID 30180900, 2018). "The findings of this study indicate that common genetic variations in the XRCC2, PHB, CDH1 and ATM genes, respectively may influence susceptibility to breast cancer among Sri Lankan postmenopausal women." (PMID 29433565, 2018). "The several data suggest that XRCC2 Arg188His polymorphism is not directly associated with breast cancer risk." (PMID 24728564, 2015). "Our results suggest that RAD51, XRCC3, and XRCC2 do not substantially contribute to breast cancer predisposition in the Finnish population." (PMID 25918678, 2015). "In literature, neither XRCC2-41657C/T nor RAD51-172G/T polymorphism is correlated with risk of breast cancer." (PMID 25743260, 2015). "Deleterious germline mutations in the XRCC2 gene have been identified in exome sequencing of familial breast cancer patients but the association was not confirmed in a larger case–control study." (PMID 25918678, 2015).